RN7SKP267 (RN7SK pseudogene 267)
Gene: Miscellaneous RNA gene on chromosome X (148,822,164 to 148,822,448, reverse strand). Ensembl gene ENSG00000222313.
Homologues: Orthologues: chimpanzee 7SK (99% identical), guinea pig 7SK (60% identical). Paralogues in human: 7SK (76% identical), RN7SKP187 (73% identical), RN7SKP81 (72% identical), RN7SKP48 (71% identical), RN7SKP62 (70% identical), RN7SKP178 (69% identical), RN7SKP227 (69% identical), RN7SKP76 (69% identical), RN7SKP174 (69% identical), RN7SKP185 (68% identical), RN7SKP118 (67% identical), RN7SKP104 (65% identical), and 284 more.